STAT3 (signal transducer and activator of transcription 3)
Diseases named in the same sentence as STAT3 in open-access papers (continued):
Sharing a sentence is not in itself a finding about the gene and the disease.
pulmonary fibrosis (continued). "Signal transducer and activator of transcription (STAT)-3, another TGF-β1-dependent stimulator of fibroblast activation, as well as HSP-47, a collagen-specific heat shock protein and an indicator of pulmonary fibrosis, were also decreased by emodin, further showing its antifibrotic activity." (PMID 33324206, 2020). "In the noncanonical TGF-β/JAK2/STAT3 pathway in lung fibrosis, miR-125a-3p plays a pivotal role." (PMID 34381815, 2021). "Interestingly, STAT3 has also been implicated in fibroblast senescence, which may participate in the etiology of pulmonary fibrosis; however, whether OSM as a STAT3-inducing cytokine activates senescence pathways directly is not yet clear." (PMID 31817403, 2019). "Daily intraperitoneal administration of JSI-124 (1 mg/kg) from day 14 to 28 reduced JAK2 and STAT3 phosphorylation as well as the increased protein levels and cell numbers in BAL, lung mass and protein, and expression of IL-6 and IL-13 secondary to lung fibrosis." (PMID 29409529, 2018). "Unlike STAT3, recent studies using knockout mice showed that STAT1 and STAT5 play key roles in promoting liver and lung fibrosis after injury." (PMID 37569586, 2023).
COVID-19 (146 papers, 2020 to 2025). A disease caused by infection with severe acute respiratory syndrome coronavirus 2. "Alongside in vitro evidence, we show an age-associated rewiring of type I IFN signaling, shifting from canonical IFN responses to proinflammatory STAT3 signaling, most prominent after age 55, mirroring the age-dependent risk of severe COVID-19." (PMID 40834853, 2025). "IL-6 in particular is associated with severe COVID-19 in humans and has been shown to facilitate neutrophil chemoattraction via STAT3 signaling in acute inflammation." (PMID 41279061, 2025). "STAT3 is a factor related to IL-6 and NF-KB, is known as an antiviral and proinflammatory mediator, and has been largely associated with COVID-19 disease severity." (PMID 38778280, 2024). "We found plasma levels of STAT3 to be associated with reduced risk of severe and hospitalized COVID-19." (PMID 40303168, 2024). "The STAT3 gene encoding transcription factor STAT3 was upregulated in ILC1s and ILC2s from COVID-19 patients." (PMID 39026668, 2024). "The identified TFs, such as FOXC1, GATA2, YY1, FOXL1, FOXO3, STAT1 and STAT3, are associated with COVID-19." (PMID 37261353, 2023). "For example, high expression of p-STAT3 was found in endothelial cells of small pulmonary veins and interstitial capillaries from COVID-19 patients; as well as increased expression of p-STAT3 in COVID-19-associated collapsed glomerulopathy biopsy samples." (PMID 36059492, 2022). "Further evidence for this was proposed in one publication where hyperactivation of STAT3 was linked to COVID-19-associated coagulopathy and lung damage." (PMID 35663932, 2022). "Genetic STAT3 gain of function (GOF) mutations result in persistent, chronic STAT3 activity, and phenocopies the changes in peripheral leukocyte populations seen in severe COVID-19, with decreased circulating levels of pDC, NK cells and Th17 lymphocytes." (PMID 35421120, 2022). "We find that although COVID-19 is associated with wholesale activation of a broad set of signaling pathways across myeloid and lymphoid cell populations, STAT3 phosphorylation predominated in both monocytes and T cells." (PMID 35421120, 2022). "Given these limitations, these data demonstrate that COVID-19 causes an acute dysregulation of the signaling landscape of circulating leukocytes, defined primarily by exaggerated phosphorylation of STAT3." (PMID 35421120, 2022). "For the two markers, the protective factor was the homozygous genotype for a minor allele: rs744166 in the STAT3 gene for susceptibility to COVID-19 and rs1898830 for the TLR2 gene for the progression of the disease to severe form." (PMID 35327350, 2022). "Activation of IL-6/JAK/STAT3 signaling was associated with COVID-19 severity, and IL-6 signaling inhibitors are reported to reduce COVID-19-associated mortality." (PMID 34067609, 2021). "Along this line, the antidepressant fluvoxamine, which has recently been shown to significantly reduce the need for hospitalization in high-risk COVID-19 patients, is known to inhibit STAT3 activity." (PMID 35056076, 2021). "This was theorized to be related to the activation of the IL-6/JAK/STAT3 pathway in the tumor microenvironment of bladder cancer patients, which further exacerbates the inflammation caused by COVID-19." (PMID 34063231, 2021). "In severe COVID-19 patients, TGFβ is associated with an uncontrolled immune reaction, in which STAT3 and SMADs genes take part." (PMID 34603282, 2021). "Mechanistically, we found that PDLIM2 was repressed in the AECs of COVID-19 patients, associating with increased NF-κB, STAT3, cell cycle checkpoints, senescence, clathrin-mediated endocytosis (CME), and pro-inflammatory cytokines but decreased RhoGDI and PPAR signaling pathways." (PMID 41000764, 2025). "The IL-6/JAK/STAT-3 axis potently potentiates inflammatory responses and may cause the decrease of lymphocytes in COVID-19." (PMID 37495990, 2023).
COVID-19 (continued). "Further studies are also needed to assess whether therapies targeting against fibroblast activation, such as inhibitors of FGFR1 or STAT3, may potentially benefit severely ill COVID-19 patients at risk for or with cardiac microthrombi." (PMID 34905515, 2022). "The production of IL-6 by epithelial cells in COVID-19 leads to the activation of STAT3; therefore, gene variants that reduce expression may have a protective effect against SARS-Cov-2." (PMID 35327350, 2022). "The addition of IFNβ to COVID-19 antiviral regimen might block IL-19 stimulated cytokines by downregulating IL-19 and attenuating STAT3 signaling, leading to better control of cytokine storm and the associated COVID-19 hyperinflammation condition." (PMID 36163397, 2022). "Importantly, STAT3 activation was shown to be involved in COVID-19 associated coagulopathy via enhancement of the expression of tissue factor and of PAI-1." (PMID 34639132, 2021). "Therefore, it is evident that COVID-19 shares the IL-6/JAK/STAT3 axis, and it is associated with several comorbid conditions such as cancers, CVDs, and CKDs, as found in our analyses." (PMID 34067609, 2021). "Our identified IL-6/JAK/STAT3 signaling is associated with CKDs and severity of COVID-19." (PMID 34067609, 2021). "In either case, our overall findings show the possibility that small molecule inhibition of proteins encoded by fibroblast regulator genes (e.g., FGFR1, STAT3) may be a novel approach to the clinical management of COVID-19 cases, be it in the acute or postacute phase of critical illness." (PMID 34905515, 2022). "In the context of COVID-19, STAT3 plays a critical role in regulating the cytokine storm and immune response, contributing to inflammation." (PMID 40408617, 2025). "STAT3 is a transcription factor having a complex involvement with COVID-19, such as inducing inflammatory responses and suppressing antiviral responses." (PMID 40303168, 2024). "COVID-19 induces a shift from STAT1 to STAT3 signaling, enhancing pro-inflammatory responses and cytokine storms." (PMID 39156288, 2024). "A cytokine storm in severe COVID-19 has been described, which involves STAT-3 upregulation of proinflammatory cytokines." (PMID 38606261, 2024). "Studies suggest that hyperactivated STAT3 is key to pathology observed in COVID-19 patients, since STAT3 acts in a positive feedback loop with plasminogen activator inhibitor (PAI-1) leading to coagulopathy characterized by intravascular thrombi." (PMID 39026668, 2024). "Both STAT3 and KLC1 were retained after colocalization analysis, however only STAT3 colocalized with severe COVID-19." (PMID 40303168, 2024). "One of the mechanisms that we identified to be commonly regulated by miRNAs expressed in COVID-19 patients is the interleukin-6/signal transducer and activator of transcription 3 (IL-6/STA3) axis, and this has been proposed previously." (PMID 36834984, 2023). "TF enrichment analysis revealed upregulation of fibrotic-associated ATF2, STAT3, and SMAD family TFs across MLCs in PPASC compared to severe COVID-19." (PMID 38259488, 2023). "STAT3 is a key transcription factor for harmful IL-6 that stimulates transforming growth factor-1beta, which plays a crucial role in pulmonary fibrosis in COVID-19 acute lung injury." (PMID 37021053, 2023). "For COVID-19, due to the occurrence of cytokine storm, the over-activation of STAT-3 can play a critical role in the COVID-19 pathogenesis." (PMID 37495990, 2023).
COVID-19 (continued). "COVID-19 induces high levels of circulating IL-6, and we found that phospho-STAT3 levels were tightly correlated with plasma IL-6 levels." (PMID 35421120, 2022). "We found near universal increases in STAT3 phosphorylation during both moderate and severe COVID-19, likely reflecting persistent STAT3 activity in both monocytes and lymphocytes." (PMID 35421120, 2022). "STAT3 is seen as one of the key elements of cytokine storm pathogenesis and other complications in COVID-19 that target IL-6." (PMID 35327350, 2022). "It appears that aberrant myelopoiesis continues after recovery from COVID-19, and IL-8 and IL-6 remain important mediators for the mobilization and expansion of STAT3 expressing M-MDSC." (PMID 35812392, 2022). "In hospitalized patients with COVID-19, some symptoms are related to aberrant STAT3 signaling such as hyperinflammatory condition, T cell lymphopenia, coagulopathy, and fibrotic status." (PMID 36111104, 2022). "In both myeloid and lymphoid cell populations, pSTAT3 levels are correlated with evidence of functional immunosuppression, suggesting STAT3 blockade as a potential therapeutic pathway to restore immunocompetence during severe COVID-19." (PMID 35421120, 2022). "These cytokines are among the key contributors to COVID-19 cytokine storm via the activation of STAT3 and MAPK inflammatory pathways." (PMID 36163397, 2022). "Following the use of the molecular docking analysis, we ultimately identified the core ferulic acid target proteins against OS and COVID-19, namely, STAT3, MAPK1, and PIK3R1." (PMID 36204096, 2022). "Based on previous studies, most of these 11 TF, especially FOXC1 and STAT3 are involved in the progression of COVID-19 and heart-related diseases." (PMID 36420258, 2022). "Kyoto Encyclopedia of Genes and Genomes (KEGG) enrichment analysis demonstrates that RIG-I and IL-6 are principally involved in the innate immune response, PI3K-AKT, and STAT3 signaling pathways in COVID-19." (PMID 36081604, 2022). "STAT3 is a potential molecular target for clinical syndromes characterized by systematic inflammation in COVID-19 in a large-scale transcriptional study." (PMID 35891565, 2022). "Therefore, STAT3 inhibitors could be potential therapy against Covid‐19 pathogenesis and cytokine storm development." (PMID 36444620, 2022). "We found that increased pSTAT3 levels in both CD4 and CD8 T cells was associated with decreased production of IFN-γ in response to CD3/CD28 stimulation, suggesting increased STAT3 activation as a mechanism for defects in T cell function during COVID-19." (PMID 35421120, 2022). "Oral inhibitor of JAK and stops the IL-6 / JAK / STAT3 pathway that can significantly reduce IL-6 levels like upadacitinib and it can be a good treatment option for COVID-19." (PMID 36111104, 2022). "In conclusion, by combining the experimental analysis and using bioinformatics tools, we constructed a circRNA/miRNA/mRNA network involved in PI3K-AKT and STAT3 signaling pathways in COVID-19." (PMID 36081604, 2022). "Although we detected upregulation of multiple signaling pathways, the specific increase in STAT3 phosphorylation during COVID-19 was striking." (PMID 35421120, 2022). "BCL6 has low activity in severe and moderate COVID-19 patients; its loss implies hyper-proliferation, followed by the expression of STAT3 to secrete IL-6, contributing to the cytokine storm in severe COVID-19 patients." (PMID 34603282, 2021). "After assembling its PPIs, 11 PPI partners (e.g., CEACAM1 and STAT3) were added to this network and salmeterol was computationally predicted to show noticeable correlations on COVID-19 (Z = −2.86, p < 10–5)." (PMID 34539756, 2021). "In this perspective, we first review the current body of knowledge on the role of STAT3 in the pathogenesis of severe COVID-19." (PMID 35056076, 2021).
COVID-19 (continued). "In severe COVID-19 cases, the gene of the transcription factor STAT3, which binds to the promoters of MMP1, MMP3, and MMP13 and regulates their expression, had eight hypermethylated CpG sites, which indicates an epigenetic inhibition of STAT3 expression." (PMID 33920915, 2021). "STAT3, which is critical for IL-6 signaling, was also expressed significantly less in patients with COVID-19 compared to patients with influenza despite the elevated levels of IL-6 circulating in these subjects." (PMID 33187979, 2020). "With this in mind, here we discuss the potential pathogenetic mechanisms and therapeutic options for COVID-19, focusing on IL-6-signal transducer and activator of transcription 3 (STAT3) signaling." (PMID 33014208, 2020). "Nevertheless, the inhibition of the signal transduction mediated by IL-6, the critical STAT3 inducer for the IL-6 amplifier, through binding to both mIL-6Rα and sIL-6Rα is a reasonable approach to consider for treating cytokine storm in COVID-19 patients." (PMID 33014208, 2020). "This crucial finding suggests that mRNA COVID-19 vaccines may stimulate the STAT3 pathway, potentially exacerbating STAT3-dependent diseases such as MF." (PMID 40733655, 2025). "STAT3, on the other hand, has been extensively studied for its roles in regulating cell growth and immune function, as well as in the development of cancer and COVID-19." (PMID 40660393, 2025). "Therefore, COVID-19 mRNA vaccines seem to have great potential to bias the STAT3 and NF-kB-dependent diseases." (PMID 40733655, 2025). "This aberrant transcriptional rewiring towards STAT3 may lead to the symptoms most typically reported in hospitalised COVID-19 patients: fast coagulopathy/thrombosis, proinflammatory conditions, profibrotic state, and T cell lymphopenia." (PMID 38628843, 2024). "Finally, miR-451a, which is known for targeting and inhibiting the IL-6/STAT3 axis, was found to be downregulated in COVID-19 patients." (PMID 36834984, 2023). "We observed that COVID-derived PBMCs and monocytes showed significantly increased levels of receptor subunit Gp130, the receptor-associated kinase JAK2, STAT1, and STAT3, and the negative regulator SOCS3 (respectively) as a function of COVID-19 disease severity." (PMID 37310504, 2023). "STAT3 inhibition was suggested as a treatment strategy for COVID-19 symptoms." (PMID 37182134, 2023). "COVID-19 could induce STAT-3 expression and then contribute to the development of M2-like macrophages, which could regulate viral replication." (PMID 36992481, 2023). "Earlier studies have found STAT3 to be increased in COVID-19 patients; therefore, its modification by 15d-PGJ2 counteracts this change and possibly could lead to restoring homeostasis in COVID-19 survivors." (PMID 37762413, 2023). "The level of mRNA encoding STAT1 and STAT3 is elevated in COVID-19 patients, regardless of disease severity, and the results suggest that IL27 signaling is activated in response to SARS-CoV-2 infection." (PMID 37310504, 2023). "Furthermore, miR-29a-3p and -29b-3p depletion has shown to increase circulatory levels of IL-6, the direct activator of the IL-6/STAT3 axis, and in patients with COVID-19 these two miRs were found to be downregulated." (PMID 36834984, 2023). "In addition, autopsy findings displayed that an activated STAT3 pathway was involved in the kidney of patients with COVID-19, which is compatible with our study." (PMID 37563112, 2023). "Therefore, the Nrf2 pathway plays a crucial role in attenuating inflammatory disorders in COVID-19 through inhibition of STAT3." (PMID 37796433, 2023). "Specifically, the dysfunctions of STAT1 and STAT3 induced by SARS-CoV-2 proteins may be the foundation of severe COVID-19 pathophysiology." (PMID 37261353, 2023). "FOXC1, YY1, GATA2, FOXL, STAT1 and STAT3 are important TFs for COVID-19." (PMID 37261353, 2023).